IL1B (interleukin 1 beta)
Diseases named in the same sentence as IL1B in open-access papers (continued):
Sharing a sentence is not in itself a finding about the gene and the disease.
liver inflammation (continued). "This study is consistent with previous findings on LPS-induced liver inflammation, confirming that LPS produces a potent inflammatory response that causes the elevation of CRP, IL-1β, and TNF-α." (PMID 39727984, 2024). "Activated inflammasome initiates caspase-1 and determines IL-1β and IL-18 pro-inflammatory cytokines production, increasing liver inflammation, fibrosis, and damage in ADL and NAFLD." (PMID 38473721, 2024). "Expression of CCL20 is induced by many inflammatory mediators, such as LPS, TNF-α, and IL-1β, and regulates liver inflammation and fibrosis by acting as a chemoattractant for lymphocytes and neutrophils." (PMID 36270295, 2023). "HDGF induces TNF-α/IL-1β/IL-6/COX-2 signaling in response to concanavalin A-induced hepatitis in vitro and in vivo." (PMID 37827291, 2023). "Conversely, hepatocytes with Nlrp3-deficiency and/or pharmacological inhibition of Nlrp3 ameliorate liver inflammation by reducing IL-1β, IL-6, and TNF-α production; they also ameliorate liver fibrosis by reducing Col1a and aSma." (PMID 37564649, 2023). "Increasing levels of LPS activate Toll-like receptor 4 signaling pathways, produce proinflammatory cytokines, such as IL-17, TNF-α, IL-6, and IL-1β, and promote liver inflammation." (PMID 38138294, 2023). "The inflammatory cytokines IL-1β and IL-6 were evaluated for their anti-inflammatory effects on alcohol-induced liver inflammation." (PMID 36788475, 2023). "The levels of hepatic pro-inflammatory markers (IL-1β and iNOS) were evaluated to determine the effect of β-Sitosterol treatment on liver inflammation." (PMID 37173727, 2023). "Pharmacological inhibition of IL-1β/IL-1R1 signaling by recombinant human IL-1R antagonist attenuated alcohol-induced liver inflammation, steatosis, and damage." (PMID 36270295, 2023). "TNF-α, IL-1β, and IL-6 are crucial cytokines involved in the occurrence and development of liver inflammation." (PMID 36144271, 2022). "In a previous study, adipose tissue-derived autologous MSCs-derived exosomes attenuated renal inflammation, decreased TNF-α, IL-6, and IL-1-β in the renal vein, and reduced the serum levels of TNF-α, IFN-γ, IL-6, IL-18, and IL-1β in a hepatitis model." (PMID 35279651, 2022). "In viral infectious hepatitis, excessive activation of the ROS/NLRP3/IL-1β axis resulted in aggravation of hepatitis." (PMID 35136014, 2022). "Ionizing calcium-binding adapter molecule 1 (Iba-1) immunostaining and Azan staining showed that the HFD-challenged Aα4KO mice developed liver inflammation and fibrosis, with elevated IL-1β, CCL2, and TGF-β1 mRNA levels." (PMID 36241662, 2022). "Activated macrophages produce pro-inflammatory factors, such as TNF-α, IL-6, and IL-1β, which induce liver inflammation and injury." (PMID 35069557, 2021). "Hepatic cytokines were higher in severe hepatitis cases (IL-1β p = 0.026, IL-23 p = 0.031, IL-8 p = 0.002, TGF-β, p= 0.037)." (PMID 34414132, 2021). "To summarize, our study demonstrated new associations between SNPs in IL1B, IL12B, IL28B, TLR4 genes and symptoms of cCMV infection such as prematurity, splenomegaly, thrombocytopenia and hepatitis respectively." (PMID 32421725, 2020). "Our study showed that IL-1β is the primary pro-inflammatory factor upregulated in DOX-induced liver inflammation, which was reduced with Cr feeding." (PMID 33374297, 2020). "In the present study, we found that hVNS regulates hepatic expression of inflammatory cytokines TNF-α, IL-1β, and IL-6 in Con-A model of hepatitis and also increases the expression of ChAT gene in the DMV neurons." (PMID 33272194, 2020). "Studies have associated the induction of hepatitis with innate immunity and acquired type 1 pro-inflammatory response including TNF-α, IL-1β, IL-6, and IL-12." (PMID 31611801, 2019).
liver inflammation (continued). "These processes collectively dampen the establishment of an effective antiviral state and provide a suitable platform for persistent infection, IL-1β production, and hepatic inflammation that contribute to ongoing immune-mediated liver injury and hepatitis." (PMID 30811485, 2019). "The levels of IL-6, TNF-α, and IL-1β in liver macerate supernatants were measured in order to evaluate the early DEN-induced liver inflammation." (PMID 31049358, 2019). "All these results indicated that rhIL-1Ra was beneficial to inhibit NLRP3 inflammasome activation apart from blocking the effects of IL-1β in ConA-induced hepatitis." (PMID 29692782, 2018). "In summary, our results identified NLRP3 inflammasome and IL-1β as central mediators in the pathogenesis of ConA-induced hepatitis." (PMID 29692782, 2018). "The proinflammatory cytokine IL-1β leads to the recruitment of invariant natural killer T (iNKT) cells, which promotes the influx of neutrophils for exacerbated hepatitis." (PMID 30319645, 2018). "In summary, our data indicated that NLRP3 inflammasome activation and IL-1β production, as well as pyroptosis strongly increased in ConA-induced hepatitis." (PMID 29692782, 2018). "In the present study, we explored the effect of IL-1β in ConA-induced hepatitis, particularly the mechanism of its activation, which was dependent on NLRP3 inflammasome." (PMID 29692782, 2018). "Here, we reported that NLRP3 and caspase-1 were required for the activation of IL-1β in a murine model of ConA-induced AIH, and mice deficient in NLRP3 or caspase-1 (NLRP3−/− or caspase-1−/−) were protected from hepatitis." (PMID 29692782, 2018). "The critical role of IL-1β/NLRP3 in the pathogenesis of ConA-induced hepatitis was also supported by an intervention study using an IL-1R antagonist that suppressed hepatic inflammation by diminishing ROS production and NLRP3 inflammasome activation." (PMID 30213101, 2018). "It is well known that the progression of hepatitis is closely associated with inflammatory factors including TNF-α, IFN-γ, IL-1β, IL-2, IL6 and iNOS." (PMID 27035150, 2016). "Previous studies have shown that IL-1β plays a crucial role in ConA-induced hepatitis and was suggested to play a role in the activation of JNK." (PMID 27293314, 2016). "Infected mice developed typical signs of hepatitis within 24–72 h post infection and during this period, pro-inflammatory cytokines, including interleukin (IL)-1β, IL-6, and tumor necrosis factor (TNF) α were secreted at the active sites of infection." (PMID 26739172, 2016). "Here, we report that aging increases sensitivity to endotoxin-induced liver inflammation and lipid accumulation through the prolonged activation of inflammasomes and subsequent IL-1β production." (PMID 25847140, 2015). "Conversely, interruption of IL-1β signals results in attenuation of the MHV-3-induced hepatitis and mortality." (PMID 26367131, 2015). "These combined data clearly demonstrate that IL-1β promotes viral amplification and exacerbates the progression of hepatitis." (PMID 26367131, 2015). "In conclusion, our data demonstrate that aging increases sensitivity to endotoxin-induced liver inflammation through the activation of inflammasomes and subsequent production of IL-1β." (PMID 25847140, 2015). "This study determined that epithelium-specific ETS (ESE)-1, an epithelium-specific transcription factor, and GP73 expressions were induced by IL-1β stimulation in vitro, and both were triggered during liver inflammation in vivo." (PMID 25530841, 2014). "We have shown that ethyl pyruvate is able to prevent Con A-induced hepatitis by down-regulating the production of inflammatory cytokines such as IL-2, IL-6, IL-1β and TNF-α." (PMID 24498418, 2014).
liver inflammation (continued). "In the same Con-A murine model of AIH, anti-rhIL1R (an antibody against the IL1 receptor) protects mice from hepatitis by inhibiting the effects of IL-1β, such as immune cell infiltration and the activation of the NLRP3 inflammasome via the elimination of ROS production." (PMID 38674122, 2024). "However, IL-1β secretion is regulated by CTLA4-Ig fusion protein, and the administration of IL-1β inhibitors in a mouse model of hepatitis upregulates the expression of PD-1 and CTLA4 in the liver." (PMID 38580797, 2024). "Liver inflammation, on the other hand, was assessed through the levels of IL-6, TNFα, and IL-1β." (PMID 37296638, 2023). "NLRP3 inflammasome activates caspase 1 and promotes the maturation and secretion of downstream pro-inflammatory cytokines such as IL-1β and IL-18, resulting in the occurrence of programed cell death (apoptosis, autophagy, pyroptosis), liver inflammation and fibrosis." (PMID 37122694, 2023). "Our experimental findings showed that in the phase of inflammation regression, HRP inhibited NF-κB by upregulating PKA activated by cAMP and inhibited TNF-α and IL-1β, which resulted in liver inflammation regression and restoration of damaged CYP2D6 and liver function." (PMID 37833431, 2023). "We then investigated whether IL-1β also affects mTOR activity in peripheral γδ T cells during CCl4-induced liver inflammation." (PMID 35361750, 2022). "The activation of the NF-κB signaling pathway leads to the phosphorylation of p65 in the nucleus, which then triggers a series of physiological or pathological effects (such as the production of inflammatory cytokines, including TNF-α, IL-1β and IL-6), which eventually leads to hepatitis." (PMID 34945677, 2021). "Moreover, JGXZ treatment attenuated the inflammatory response in NAFLD model rats, manifesting as mild lobular liver inflammation and reduced expression of proinflammatory cytokines (IL-6, IL-1β, and TNF-α) in the serum and liver." (PMID 33824675, 2021). "In addition to the altered intestinal parameters, aged mice also demonstrated significant alcohol-induced liver inflammation compared to young mice, with increased inflammatory foci and IL-1β mRNA expression after 4 weeks of multi-day ethanol exposure." (PMID 34556145, 2021). "Furthermore, the influence of the studied compound on the levels of several other relevant cytokines, such as IL-1β, IL-4, IL-12, and IL-17A, was investigated in mice with ConA-induced hepatitis." (PMID 33919375, 2021). "Importantly, treatment with a blocking anti-OX40L monoclonal antibody at the time of ConA injection prevented the hepatitis, the rise in IL-1β and IL-18 expression, and the inflammatory response." (PMID 33353156, 2020). "Furthermore, quantitative RT-PCR indicated a decreased expression of hepatitis-related genes, such as tumor necrosis factor-α, IL-6, and IL-1β in OVX rats after BCE treatment." (PMID 32466275, 2020). "The results suggested that CyA might inhibit Con A-induced liver inflammation by lowering elevated levels of IL-1β and ICAM-1." (PMID 30893870, 2019). "The IL-1β /NLRP3 inflammasome cascade may therefore present an attractive target for treating liver disease induced by HCV and other causes of liver inflammation." (PMID 30811485, 2019). "In conclusion, our results demonstrated that NLRP3 inflammasome-dependent IL-1β production was crucial in the pathogenesis of ConA-induced hepatitis, which shed light on the development of promising therapeutic strategies for AIH by blocking NLRP3 inflammasome and IL-1β." (PMID 29692782, 2018). "In ConA-induced hepatitis, lack of IL-33 was associated with increased hepatic IL-1β expression and more severe liver injury, however, a possible link between the NLRP3 inflammasome and IL-33 was not analyzed." (PMID 30213101, 2018).
liver inflammation (continued). "Upon sensing noxious signals, NLRP3 recruits pro-caspase-1 and the adaptor molecule ASC (apoptotic specklike protein-containing CARD), resulting in activation of caspase-1 as well as secretion of IL-1β and interleukin-18 (IL-18), which play a critical role in promoting liver inflammation." (PMID 29692782, 2018). "First, we assessed whether NLRP3 inflammasome and IL-1β were activated in ConA-induced hepatitis, western blot was employed to observe protein expression of NLRP3 inflammasome and IL-1β." (PMID 29692782, 2018). "Moreover, viral infected animals in deficiencies of NLRP3 and Caspase-1, two essential components of the inflammasome complex, also have reduced IL-1β induction along with ameliorated hepatitis." (PMID 26367131, 2015). "Additionally, a recent study has also reported that the administration of DSS changed the expression of pro-and anti-inflammatory cytokines such as IL-1β, IL-10, and TGFb-2, suggesting that intestinal inflammation led to liver inflammation, thus, these results supported our finding again." (PMID 34603071, 2021). "Moreover, NLRP3−/− and caspase-1−/− mice displayed downregulated IL-1β expression and diminished hepatitis, indicating that NLRP3 and caspase-1 were essentially required for IL-1β secretion and also contributed to the development of ConA-induced hepatitis in mice." (PMID 29692782, 2018). "Besides, hepatic macrophages can release many proinflammatory cytokines such as tumor necrosis factor-α (TNF-α), interleukin-1β (IL-1β), and IL-6 which may induce liver cellular apoptosis and aggravate liver inflammation." (PMID 29743924, 2018). "In the livers of ConA‐induced hepatitis mice, the expression levels of NLRP3, CASP1, and IL1B are significantly upregulated." (PMID 41503678, 2026). "RhIL-1RAs reduce the severity of ConA-induced hepatitis by eliminating ROS, inhibiting NLRP3 inflammasome assembly and activation, preventing pyroptosis, and competing with IL-1β." (PMID 39917567, 2025). "SP effectively suppressed IKK, IκB, and p65 phosphorylation, modulated the NF-κB signaling pathway, downregulated IL-1β, IL-6, and TNF-α expression, and mitigated EtOH-induced liver inflammation." (PMID 40362898, 2025). "The serum IL-1β, IL-6, TNF-α, TBIL, DBIL, ALT, AST and ALP levels decreased with rats treated with PZW where reduced liver inflammation halted its fibrosis and improved overall hepatic health." (PMID 41293246, 2025). "Cd can activate the NLRP3 inflammasome, promoting liver inflammation and hepatitis, particularly severe during early estrus, by increasing TNF-α, MCP-1, and pro-inflammatory cytokines such as IL-1α, IL-1β, and IL-18." (PMID 39255638, 2024). "In ConA-induced hepatitis, the expression of the NLRP3 inflammasome and the levels of activated caspase-1, IL-1β, and lactate dehydrogenase are elevated in the blood." (PMID 36969233, 2023). "In this study, BCG immunostimulation induced hepatitis, characterized by inflammatory cell infiltration to form large and small clumps, increased liver weight, increased TNF-α and IL-1β, and increased AST/ALT." (PMID 37833431, 2023). "The main mechanism of action by which IL-1β was triggered by ROS combined with TNF-α to activate NF-κB to induce FGL2 expression, which intensifies the progression of hepatitis." (PMID 35136014, 2022). "Treatment with MCC950 decreased the serum levels of IL-1β and IL-6, ALT/AST, and the severity of liver inflammation." (PMID 35566282, 2022). "We detected the transcription and translation of inflammatory factors such as IL-1β and TNF-α in the liver, and proved the inhibitory effect of GFL on BDL-induced hepatitis." (PMID 36278176, 2022). "The results showed that IL-1β and IL-6 levels were increased in the APKO-DEN hepatitis mice compared with WT-DEN mice, but the IL-12p70 and TNFα levels did not change significantly." (PMID 33558702, 2022).
liver inflammation (continued). "Overproduction of inflammatory cytokines such as IL-1β, IL-18, IL-6, and TNF-α during the activation of IRI-induced immune responses is referred to as liver inflammation." (PMID 35978104, 2022). "Due to the production of a large number of reactive oxygen free radicals, oxidative stress will promote the release of inflammatory factors, such as IL-1β, IL-6 and TNF-α, which leads to liver inflammation." (PMID 34828972, 2021). "Both IFN-γ and IL-1β in serum and liver of the day 28 group were significantly higher than those in the day 14 group, which means that a persistent HCP diet aggravated liver inflammation in geese." (PMID 34552978, 2021). "Interleukin 1 Beta (IL1B) was up-regulated along with GHR, and there is evidence that pro-inflammatory cytokines such as IL-1β are involved in hepatic growth hormone resistance during inflammation." (PMID 32101552, 2020). "The pro-inflammatory markers IL-1α, IL-1β, IL-6, TNF, ICAM-1, and VCAM-1 were all significantly upregulated under both hepatitis models." (PMID 29445190, 2018). "IL-1β also appears to be involved in the pathology of human AIH since IL-1β levels were elevated in AIH patients and correlated with aggravation of hepatitis." (PMID 30213101, 2018). "Recent clinical studies demonstrated that the expression of IL-1β in patients with AIH was significantly increased and correlated with aggravation of hepatitis." (PMID 29692782, 2018). "Additionally, both pro-inflammatory and anti-inflammatory genes, such as Cd163, Ho-1, Il-1β, Il-10, and Ccl5, along with CD163 and HO-1 protein expression, were markedly suppressed, supporting the notion of alleviated liver inflammation." (PMID 41522337, 2026). "Currently, inflammatory markers such as CRP, IL-1β, and TNF-α are widely used to evaluate hepatitis, but these markers may lack specificity." (PMID 39996800, 2025). "The results showed that IL-1β, IL-6, and TNF-α levels were observably increased in the M group, and QJ treatment significantly downregulated this change, which further confirmed that QJ inhibited CCl4-induced liver inflammation." (PMID 38606180, 2024). "Moreover, cynaroside decreased the expression of IL-1β, IL-6 and TNF-α,and inhibited HMGB1 in cecal ligation and puncture-induced liver inflammation." (PMID 38835771, 2024). "The IL-1β/TNF-α/NF-κB pathway is activated during the inflammation initiation process, and HRP can downregulate its activation in a dose-dependent manner, implying that this pathway is involved in the initiation of hepatitis." (PMID 37833431, 2023). "It was found that MTX significantly induced hepatitis and hepatocellular damage, as shown by abnormal histological findings and liver dysfunction (ALT and AST), with up-regulation of the inflammatory mediators NF-κB-p65 and IL-1β." (PMID 36422565, 2022). "DIO mice expressed higher TNF-α and IL-1β levels in the adipose tissue after 24 weeks and in the liver after 40 weeks of consuming DIO, indicating that IR was established before the development of liver inflammation." (PMID 35889863, 2022). "Furthermore, we detected pro-inflammatory cytokines TNF, IL-1β, IL-12p70, IFN-γ, IL-6, IL-2, and IL-17A corresponding with ConA-induced hepatitis and found that pro-inflammatory factors all rise at 6 h after ConA injection." (PMID 36248904, 2022). "The mRNA expression of IL-1β, IL-6, TNF-α, TGF-β, α-SMA, Collagen I, Collagen IV, and Fibronectin in the CCl4 group were significantly increased compared with the control group, demonstrated liver inflammation and fibrosis." (PMID 35842576, 2022). "The levels of several other inflammatory mediators, i.e., IL-1β, IL-4, IL-10, IL-12, and IL-17A, were measured in the serum of mice with ConA-induced hepatitis in the presence and absence of GRMS-55." (PMID 33919375, 2021).